NANOG (Nanog homeobox)
Diseases named in the same sentence as NANOG in open-access papers (continued):
Sharing a sentence is not in itself a finding about the gene and the disease.
cancer (continued). "Also, NEAT1 and POUF51 genes followed the same trend as NANOG in the MVA, indicating that the pluripotency increasing capacity of the cancer microenvironments was associated with genuine cancer aggressiveness and disease recurrences in the patients." (PMID 35565301, 2022). "This hypothesis is borne out by previous studies demonstrating that DNMT3A/3B cooperate in OCT-3/4 and NANOG promotor methylation during the differentiation of embryonic stem cells and carcinoma cells." (PMID 35081981, 2022). "In addition, transwell assays demonstrated that NANOG regulates cancer cell migration through the SDF1/CXCR4 pathway." (PMID 34638956, 2021). "Transcription factor genes (OCT4, KLF4, SOX2, MYC, NANOG, and REX1) and cell surface markers (CD133, LGR5), which are associated with embryonic stem cells, induced pluripotent stem cells, and cancer stem cells, have been selected for measuring expression levels from the selected tissues." (PMID 34452555, 2021). "Therefore, targeting OCT4 or NANOG should be a rational strategy for therapeutic application in certain types of cancers." (PMID 34488885, 2021). "Previous studies have shown that NANOG is closely related to the poor prognosis of cancers." (PMID 34150636, 2021). "NANOG is a homeobox domain transcription factor, which is a key regulator of embryonic development and cellular reprogramming, and is broadly expressed in various cancers." (PMID 34834576, 2021). "The downregulation of SPN in breast cancer cell lines increases the tumorigenic properties and cancer stem cell properties, such as the formation of tumorspheres and the expression of stem cell genes (NANOG, OCT4, SOX2 and KLF4), whereas the overexpression of SPN causes the opposite effect 17,18." (PMID 33537097, 2021). "NANOG as a transcriptional regulator is highly expressed in some cancer stem cells." (PMID 34123777, 2021). "Cancer stem cell markers also include NANOG, ALDH1, SOX2, OCT4, LGR5, CD44, and CD133; therefore, stemness may be judged by the expression of these markers." (PMID 34725550, 2021). "In conclusion, our results suggest that the role of NANOG in cancer stem cell migration may be due to the direct regulation of the CXCR4 gene." (PMID 34638956, 2021). "NANOG, OCT4, and SOX2 mainly promote tumorigenesis by regulating the CSCs, and therefore high expression of these stem cell factors is associated with poorer outcomes in numerous cancers." (PMID 34573355, 2021). "In addition to being expressed in ESCs, NANOG has been shown to be expressed in many types of human cancers." (PMID 35008480, 2021). "Moreover, expressions of stemness genes, such as OCT4, SOX2, and NANOG, are often deployed to measure cancer stemness." (PMID 34760886, 2021). "NANOG is also thought to assist OCT4 in cancer and epithelial-to-mesenchymal transition in LA." (PMID 34685477, 2021). "The upregulation of HIF under hypoxia microenvironment has been shown to induce the expression of known pluripotent stemness factors, such as KLF4, MYC, OCT4, SOX2, and NANOG, to reprogram towards a cancer stem cell (CSC) phenotype and to influence the expansion of CSC populations." (PMID 34798868, 2021). "Understanding the roles of NANOG in cancer stemness and lineage switch may benefit therapeutic development for a wide range of human diseases." (PMID 33439550, 2021). "NANOG is known to be a marker of poor prognosis in several cancers." (PMID 33678155, 2021). "Aberrant NANOG expression is commonly found in multiple cancer types including lung ADC." (PMID 33439550, 2021). "It was shown that the increase of OCT4, SOX2, and NANOG could enhance the stemness and determine the malignant phenotypes in a wide range of cancers." (PMID 34708581, 2021). "Moreover, the expression levels of the cancer stemness markers, NANOG, CD44, and KLF4, were markedly higher in 3D spheroids than in 2D monolayers." (PMID 34948357, 2021).
cancer (continued). "Another study suggested that the Rb/E2f complex could trigger global chromatin repression and NANOG expression, thus promoting cancer cell transition to the G0 phase of the cell cycle." (PMID 37304648, 2021). "Pluripotency factors OCT4 and SOX2 and NANOG are markers of cancer stem cells." (PMID 32664372, 2020). "Hypoxia signalling can induce HIF-dependent expression of known pluripotent factors, such as KLF4, MYC, OCT4, SOX2, and NANOG, which have an important role in the dedifferentiation process under hypoxic conditions, inducing cancer stemness and repressing cancer cell differentiation." (PMID 33339101, 2020). "Pluripotency factors, such as OCT4 or NANOG, are master regulators of dedifferentiation, and therefore may be critical for the clinical outcome of malignant tumors." (PMID 32664372, 2020). "Of note, NANOG overexpression-induced cancer stem-like properties and gefitinib resistance could be obviously reversed by knocking-down IRX4." (PMID 32820157, 2020). "Interestingly, cells with extremely high expression of NANOG, which can represent cancer stem cells, were enriched upon ROS-inducing antimycin A treatment." (PMID 32664372, 2020). "In line with this, it has been demonstrated that nicotine plays a critical role in the development of tobacco-induced cancers by increasing the expression of various CSC markers NANOG, OCT4, CD44, and BMI-1 and regulating CSC properties and tumorigenic potential in HNSCC models in vitro and in vivo." (PMID 32635524, 2020). "The known interactions between TEs and pluripotency factors such as NANOG and OCTt4 during early development, along with the expression of some placental-specific TE-derived transcripts in cancer support a possible link between TEs and dedifferentiation of tumor cells." (PMID 32432029, 2020). "In addition to being a key regulator of pluripotency, NANOG has been described as a crucial transcription factor in various types of cancer." (PMID 32580970, 2020). "However, NANOG expression is detectable in a proportion of cancer cells that exhibit stem cell-like properties." (PMID 32733958, 2020). "Therefore, the NANOG protein can be coded by two different genes in human cancer cells, while only one NANOG protein is expressed in mouse cancer cells." (PMID 32197405, 2020). "Knockdown of NANOG inhibited the expression of CD133 and restored gefitinib cytotoxicity, and NANOG overexpression-induced cancer stem-like properties and gefitinib resistance could be obviously reversed by knocking-down IRX4." (PMID 32820157, 2020). "Furthermore, knockdown of PKM2 combined with IR markedly reduced the expression of several cancer stem cell biomarkers in vitro, including NANOG, OCT4, SOX2, and Bmi1." (PMID 31114449, 2019). "We have thus explored the possibility that chimeric repressors, widely used in developmental studies, could be useful as potential anti-cancer agents targeting stemness, focusing in this study on NANOG." (PMID 30846719, 2019). "Tumorigenic cancer cells might evade NK cell attack by regulating membrane surface proteins, and we hypothesized that NANOG upregulates NK cell inhibitory factors or downregulates NK cell activation factors in PCa cells." (PMID 31619256, 2019). "Although it is unclear why such an opposite transcription regulation is modulated by NANOG between these cancers, the components of transcription factor complex might differ depending on the type of cancer." (PMID 31619256, 2019). "Similarly, OCT4, SOX2, and NANOG increased the ability to form spheres indicating a role in obtaining cancer stem cell properties." (PMID 31885625, 2019). "When Colo-320 and MCF-7 cancer cell lines were cultured in ESC conditioned medium, they exhibited re-expression of pluripotency-associated markers, including Oct-4, NANOG, and SOX2 and reduction of tumorigenicity in vitro, indicating the successful reprogramming from malignancy into benignity." (PMID 31464654, 2019).
cancer (continued). "Additionally, we also observed an up-regulation in some cancer stem cell markers such as NANOG, ABCC2, ABCC5, CD44 and KLF450,51." (PMID 31597943, 2019). "To further understand how DEGs were regulated, we analysed transcription factor (TF) binding using Enrichr and observed that DEGs were enriched for targets of TFs associated with self-renewal and cancer stem cell function (SUZ12, SOX2, REST, EZH2, SMAD4 and NANOG)." (PMID 31014368, 2019). "In addition, we used this 94 aa portion plus the adjacent WR dimerization domain to enhance function if NANOG were to act as a dimer in cancer cells as it does in ESCs35,36." (PMID 30846719, 2019). "Importantly, NANOG1 and NANOGP8, which is a retrogene, encode NANOG proteins that differ by 1-2 conservative amino acid changes indicating that functional NANOG protein can be made from two genes in human cancer cells." (PMID 30846719, 2019). "To understand contributing factors that may be supporting NANOG activation and cancer stemness, we also checked β‐catenin and HIF‐1α as a known activator of P4HA2." (PMID 31268606, 2019). "The strength of NANOG expression could affect the conversion of cancer cell density from [epi] to [strom]." (PMID 31146720, 2019). "The two mRNA markers SPINT2 and NANOG that are upregulated in cancer ascites relative to peritoneal fluids may have potential as diagnostic biomarkers." (PMID 29499737, 2018). "SOX2 and NANOG are transcription factors and biomarkers for cancer stem cells (CSCs)." (PMID 29963272, 2018). "Further, systematic epigenomic analysis of OIP5-AS1 promoter revealed binding motifs for MYC, NANOG and KLF4 suggesting that OIP5-AS1 could be transactivated by stemness-associated transcription factors in cancer." (PMID 29728583, 2018). "DC vaccination against NANOG could solve this problem by specifically removing CSCs that fuel cancer growth." (PMID 29971070, 2018). "Our group has previously reported increased expression levels of NANOG in GBM cancer stem cells, and have postulated that NANOG may be an ideal marker for the identification of cancer stem cells." (PMID 29787607, 2018). "Also, evidence has revealed that the SOX2 and NANOG are critical factors in conferring certain CSC properties to cancer cells such as self-renewal, metastasis and drug resistance." (PMID 29963272, 2018). "In addition, SOX2, OCT4 and NANOG are transcription factors that play key roles in maintaining the pluripotency of embryonic stem cells and cancer stem cells." (PMID 29552304, 2018). "Through a process known as plasticity, differentiated cancer cells become CSCs by re-expressing NANOG, which also occurs in non-pathogenic cells." (PMID 29971070, 2018). "Interestingly, here we showed that NANOG and c-MYC expression, as stemness-associated factors, were detected in these OCSCs and that their cancer stem-like properties were negatively regulated by STON2 expression." (PMID 30518424, 2018). "The regulation of NANOG expression itself in cancer requires a more in-depth understanding." (PMID 29422613, 2018). "In addition, the protein expression levels of the genes related to cancer stemness, including NANOG and SOX2 were significantly downregulated in RIF1-knockdown EOC cells and were upregulated in RIF1-overexpressed EOC cells." (PMID 30075819, 2018). "The critical roles of NANOG and NANOGP8 in cancer progression leads the association of these genes with exosomes to be significant, and may allow for exosomal NANOG to function as a powerful diagnostic biomarker." (PMID 29787607, 2018).
cancer (continued). "We then focused on the expression of a pluripotency factor, NANOG, because previous reports showed that a downstream effector in the Hh pathway, GLI, directly binds to the NANOG promoter and that the GLI-NANOG axis promotes stemness and growth in several cancers." (PMID 28245563, 2017). "These lncRNAs could regulate the expression of CSC-related transcriptional factors, such as SOX2, OCT4, and NANOG, in colorectal, prostate, bladder, breast, liver, and other cancer types." (PMID 29299179, 2017). "However, NANOG has occasionally been detected in the cytoplasm of highly primitive cells or invasive cancer cells." (PMID 29113102, 2017). "Studies have shown that cancer cells with stem cell characteristics, especially the OCT4- and NANOG-positive cancer cells, may undergo epithelial-mesenchymal transition (EMT) and rapid metastasis." (PMID 29069758, 2017). "NANOG induced the expression of cancer-related genes like CD133 and aldehyde dehydrogenase 1A1." (PMID 29259714, 2017). "Accordingly, we demonstrate that senescent HCT116 cells possess several properties of cancer stem cells, namely: elevated NANOG expression, increased Hoechst 33342 exclusion, increased CD24 expression, an ability to divide asymmetrically, clonogenic and spheroid-forming potential." (PMID 28030837, 2017). "NANOG is overexpressed in oral squamous cell carcinoma and other types of cancers." (PMID 29259714, 2017). "Increases in expression of the progenitor cell markers SOX2, SOX9 and NANOG in A549 cells seen in the present study could be indicative of the presence of such a cancer stem cell population." (PMID 27792742, 2016). "Moreover, the small round cells and tumour-like structures were positively stained for pluripotency-related marker NANOG, thus further indicating that the small round cells were indeed putative cancer stem cells." (PMID 27703207, 2016). "Accordingly, cancer cells present some remarkable similarities with embryonic stem cells, including unlimited proliferation and self-renewal, and the expression of pluripotency genes, such as NANOG, OCT4 or SOX2." (PMID 26203771, 2015). "Cancer cells present some similarities with embryonic stem cells, including unlimited proliferation and self-renewal, and the expression of pluripotency genes, such as NANOG, OCT4 or SOX24." (PMID 25988972, 2015). "Thus our study reveals MUC16-Cter-JAK2-LMO2/NANOG axis to be a novel pathway responsible for mediating enrichment of PC cancer stem-like cells." (PMID 25691062, 2015). "Indeed, current evidence indicates some specific pluripotency genes, such as OCT4, SOX2 and NANOG, expressed in specific human cancer types as putative regulators of embryonic stem cell (ESC) identity." (PMID 25127259, 2014). "Among TFs that control AFP gene transcription in a cooperative fashion stands NANOG, a stemness factor expressed in pluripotent and cancer stem cells, and which is one of the major protein protagonists involved in the cell allostatic decision between self-renewal and differentiation." (PMID 25502816, 2014). "Finally, de novo aberrantly methylated genes in Y-iPSCs were enriched for NANOG targets that are also aberrantly methylated in some cancers." (PMID 25408883, 2014). "Thereafter, NANOG-positive undifferentiated cancer cells may be maintained in metastatic foci and disappear from primary foci." (PMID 24348816, 2014). "In this study, we characterized the epigenetic regulation of the pluripotency-associated genes NANOG, OCT4, c-MYC, KLF4, and SOX2 in a variety of cancer cell lines and in primary tumor samples, and investigated the re-activation of pluripotency regulatory circuits in cancer progression." (PMID 24023739, 2013). "OCT4 and NANOG are expressed in lung stem cells, and their co-expression may enhance malignancy by inducing cancer stem cell-like properties." (PMID 24206786, 2013).
cancer (continued). "The reprogramming factors OCT4, SOX2, NANOG, KLF4, c-MYC, and LIN28 have also been suggested to be oncogenes and may be implicated in the development of several cancers." (PMID 24040120, 2013). "Demethylation of NANOG promoter was observed in CD133+high cancer cells." (PMID 24023739, 2013). "In addition, we demonstrated a cross-regulation between OCT4 and NANOG in cancer cells via reprogramming of promoter methylation." (PMID 24023739, 2013). "In addition to its presence in embryonic stem cells, the NANOG protein is present in cancer stem cells (CSCs) in a variety of human cancers." (PMID 23173096, 2012). "Importantly, knockdown of NANOG/NANOGP8 mRNA in cancer cells inhibits tumorigenesis and clonogenic growth of breast, colon, prostate, and gastrointestinal cancer cell lines." (PMID 23173096, 2012). "We suggest that OCT4 and NANOG transcripts detected in all cancer lines studied may be relevant to the pseudogenes and have no functional meaning." (PMID 21785609, 2011). "Notably, embryonic transcription factors, including SRY-box transcription factor 2 (SOX2), octamer-binding transcription factor 4 (OCT4), and Nanog homeobox (NANOG), are vital for preserving the self-renewal capacity and undifferentiated state of CSCs in various cancers." (PMID 41522355, 2026). "Further, gene expression of cancer cells showed upregulation of stemness associated genes NANOG, OCT4, CK14 and CD44 in two different cancer cell lines exposed to CM of TGF-CAF compared to that of UT-CAF; suggesting the possibility of induction of stemness in cancer cells by TGF-CAF." (PMID 40349056, 2025). "Understanding NANOG’s role may lead to it becoming a therapeutic target to halt cancer progression." (PMID 41465103, 2025). "This phenomenon may be due to the relatively conventional signaling network that governs the stemness/differentiation switch among distinct stem cell, as evidenced by the reductive expression of stemness-related ALDH1 and NANOG in cancer stem-like cell and OCT4 in pluripotent stem cell." (PMID 40708945, 2025). "The robust deterministic process of single-cell cancer induction that we uncovered suggests that the aberrant reactivation of Epi-Driver genes involved in reprogramming/pluripotency (such as VENTX/NANOG, POU5/OCT4) might be relevant to the irreversible malignant transformation of a cell." (PMID 40130618, 2025). "In cancer stem cells (CSCs), STAT3 gain-of-function mutations or persistent activation further amplify these effects by promoting the expression of stemness-related transcription factors such as NANOG, SOX2, and OCT4, which are critical for maintaining the CSC phenotype." (PMID 40140827, 2025). "Targeting Gli may reduce the stemness of cancer cells via indirect targeting of NANOG." (PMID 40804837, 2025). "Additionally, cancer stemness was established by increased expression of NANOG." (PMID 38170015, 2023). "Additionally, NANOG-positive stem cell-like cancer cells could be used as a new antitumoral treatment target if validated in mechanistic and clinical studies." (PMID 37461005, 2023). "Similarly, NANOG has been established as a marker for cancer stem cells." (PMID 36968194, 2023). "Indeed, NANOG plays a vital role in CSCs (cancer stem cells)." (PMID 36003795, 2022). "Interestingly, there appears to be a mutual regulation of CXCR4 and NANOG in stem-like cancer cells, which could be mediated by PI3K/Akt/NF-κB and SHH/Gli1 pathways." (PMID 36118530, 2022). "It is unclear whether cancer cells utilize the exact mechanisms to regulate NANOG expression." (PMID 36564568, 2022). "Interestingly, results from previous studies indicated that these stemness factors including NANOG could induce immune evasion in various cancers by modulating the T cell–mediated antitumor response." (PMID 35104240, 2022).